NUDT22 (nudix hydrolase 22)
Description:
Pyrophosphatase hydrolyzing the diphosphate bond in the nucleotide-sugars UDP-glucose and UDP-galactose with a preference for the former, yielding glucose 1-phosphate or galactose 1-phosphate and UMP.
Synonyms: MGC13045
Tractability: Small molecule: a structure with a bound ligand is known. PROTAC: ubiquitination databases record sites on it.
Gene: Protein-coding gene on chromosome 11 (64,225,941 to 64,230,686, forward strand). Ensembl gene ENSG00000149761.
Subcellular location (Human Protein Atlas): Nucleoplasm
Gene Ontology:
Molecular function: protein binding; UDP-sugar diphosphatase activity
Cellular component: nucleoplasm
Genetic constraint (gnomAD): Loss-of-function variants: 25 observed, 28.53 expected, observed/expected ratio (o/e) 0.88, 90% interval 0.64 to 1.22. The upper end of that interval is the gene's LOEUF score, 1.22, which puts it in group 5 of 6, group 1 being the genes least tolerant of losing a copy. Missense variants: 358 observed, 368.15 expected, observed/expected ratio (o/e) 0.97, 90% interval 0.89 to 1.06. Synonymous variants: 175 observed, 163.64 expected, observed/expected ratio (o/e) 1.07, 90% interval 0.94 to 1.21.
Homologues: Orthologues: chimpanzee NUDT22 (99% identical), macaque NUDT22 (87% identical), dog NUDT22 (84% identical), rabbit NUDT22 (84% identical), pig NUDT22 (83% identical), mouse Nudt22 (82% identical), rat Nudt22 (82% identical), guinea pig NUDT22 (81% identical), tropical clawed frog nudt22 (53% identical), zebrafish nudt22 (49% identical).
Diseases named in the same sentence as NUDT22 in open-access papers:
NUDT22 is named in the same sentence as 9 diseases in open-access papers, as found by Europe PMC text mining. Sharing a sentence is not in itself a finding about the gene and the disease. The quoted sentences say what the papers report.
breast carcinoma (1 paper, 2023). "Our observed elevated NUDT22 expression we observed in other cancer types was further reinforced in breast cancer, with all major pyrimidine metabolism enzymes following the same trend." (PMID 36871087, 2023). "To transfer our findings into an orthotopic mouse breast cancer in vivo xenograft model, we injected engineered luc2 NUDT22 KO MCF7 cells into female NOD/SCID mice and monitored tumour growth by IVIS imaging in live animals." (PMID 36871087, 2023). "In addition, breast cancer patients with NUDT22 alterations or high NUDT22 expression levels have a worse prognosis in overall survival." (PMID 36871087, 2023). "To test whether our results in U2OS cells translate in breast cancer cells we generated NUDT22 KO MCF7 cells." (PMID 36871087, 2023).
lung carcinoma (1 paper, 2023). "UDP-glucose, the substrate for NUDT22, has been linked to metastatic progression of lung cancer cells by directly interfering with translation of the EMT-promoting gene SNAI1." (PMID 36871087, 2023).
osteosarcoma (1 paper, 2023). A usually aggressive malignant bone-forming mesenchymal neoplasm, predominantly affecting adolescents and young adults. "qRT-PCR analysis revealed that all scenarios led to a significant increase in NUDT22 expression by qRT-PCR and western blot in the fibroblast cell lines HA1EB, BJ, and hTERT-RPE1 as well as the osteosarcoma U2OS cell line." (PMID 36871087, 2023).
cancer (2 papers, 2017 to 2023). A tumor composed of atypical neoplastic, often pleomorphic cells that invade other tissues. "NUDT22-deficient cancer cells suffer from growth retardation, S-phase delay, and slower DNA replication fork speed." (PMID 36871087, 2023). "Conversely, NUDT22 deficiency sensitizes cells to de novo pyrimidine synthesis inhibition in vitro and reduces cancer growth in vivo." (PMID 36871087, 2023). "NUDT22-deficient cancer cells have diminished nucleotide pools and display hallmarks of replication stress, such as reduced replication fork speed, delayed S-phase progression, cell cycle checkpoint activation, increased DNA damage and single-stranded DNA." (PMID 36871087, 2023). "NUDT22 expression is consistently elevated in cancer tissues and high NUDT22 expression correlates with worse survival outcomes in patients indicating an increased dependency of cancer cells to NUDT22." (PMID 36871087, 2023). "To better understand the overall significance of NUDT22 in cancer, we interrogated the TCGA and GTEx databases for differential gene expression of NUDT22 and genes involved in pyrimidine biosynthesis." (PMID 36871087, 2023). "In conclusion, NUDT22 maintains pyrimidine supply in cancer cells and depletion of NUDT22 leads to genome instability." (PMID 36871087, 2023). "Pan-cancer analysis clearly indicated increased NUDT22 expression levels in cancer tissue compared to normal tissue." (PMID 36871087, 2023). "It is tempting to hypothesize that the observed differences in cancer cell lines may be due to an increased metabolic demand in cancer, which is also suggested by the increased NUDT22 expression in cancer tissues but needs to be further investigated." (PMID 36871087, 2023). "Finally, our in vivo findings provide a clear rationale for the preclinical translation of targeting NUDT22 in cancer." (PMID 36871087, 2023). "Inhibition/deletion of NUDT22 could therefore potentially suppress metastatic potential and simultaneously increase DNA damage burden in cancer cells by reducing UMP and keeping UDP-glucose levels high." (PMID 36871087, 2023). "Targeting NUDT22 therefore has high potential for therapeutic applications in cancer therapy." (PMID 36871087, 2023). "Here, we present evidence that NUDT22 is a previously unknown important regulator of a cellular salvage pathway with special significance in cancer." (PMID 36871087, 2023). "Co-targeting of pyrimidine salvage and de novo synthesis for cancer therapy has recently received renewed attention, and our data suggest that targeting pyrimidine de novo synthesis combined with NUDT22 inhibition might be an interesting novel therapeutic approach in the future." (PMID 36871087, 2023). "To this end we compared the cellular role of NUDT22 in U2OS cancer and hTERT-RPE1 fibroblast NUDT22 KO cell lines." (PMID 36871087, 2023). "However, a distinct cluster appeared when comparing cancer vs normal tissues, which contained NUDT1, NUDT5, NUDT8, NUDT14, and NUDT22, confirming a potential role of these NUDIX hydrolases in cancer." (PMID 29142246, 2017).
tumours (1 paper, 2023).
NUDT22 also shares sentences with these, for which no sentence is quoted: chronic myeloid leukemia (1 paper); hematologic disorder (1); lung (1); lung adenocarcinoma (1).